CGAS (cyclic GMP-AMP synthase)
Diseases named in the same sentence as CGAS in open-access papers (continued):
Sharing a sentence is not in itself a finding about the gene and the disease.
tumor (continued). "Besides, all of O2, OMs and cGAS-STING activation could promote the polarization of macrophages towards anti-tumor M1." (PMID 38831378, 2024). "Our current findings suggest the potential of tumor cell-intrinsic cGAS–STING as a novel biomarker for predicting the efficacy of immunotherapy using ICIs in GC and might provide new insights for treating patients with GC by targeting the tumor cell-intrinsic cGAS–STING pathway." (PMID 39242811, 2024). "Upregulation of PD-L1 in tumor cells and in the tumor microenvironment by radiotherapy is a complex mechanism and thought to be through four pathways: Interferon γ signaling, epidermal growth factor receptor pathway, DNA damage signaling pathway, and cGAS-STING pathway." (PMID 39026981, 2024). "Furthermore, CS/MTO-Cu@AMI enhances anti-tumor immunity by stimulating the cGAS-STING pathway, which plays a critical role in promoting immune surveillance and response against tumors, making it a promising candidate for combination therapies targeting immune checkpoints." (PMID 39867656, 2024). "CDNs are produced by cGAS upon binding to cytosolic DNA, such as viral DNA or self-DNA originating from the nucleus or mitochondria, which may occur following cell division, as a result of DNA damage, or from damaged tumor cells." (PMID 39456148, 2024). "The cyclic GMP-AMP synthase (cGAS)-stimulator of interferon genes (STING) pathway has gained prominence as a potential target for improving LC immunotherapy due to its pivotal role in enhancing anti-tumor immune responses, augmenting tumor antigen presentation, and promoting T cell infiltration." (PMID 39588006, 2024). "Rapid activation of cGAS-STING signaling could robustly inhibit tumor growth; however, tumor-derived cGAMP and chronic inflammation caused by DNA-damage response (DDR), chromosomal instability (CIN), mtDNA release, and dying cells may promote tumor progression." (PMID 39304793, 2024). "Therefore, host STING activation and its vascular normalizing effect may be controlled by tumor cGAS or host cGAS." (PMID 38177099, 2024). "Nonetheless, the conducted radiation dose determines whether radiotherapy causes cGAS-STING- mediated anti-tumor effects or not." (PMID 38347787, 2024). "Therefore, the tumor cell-intrinsic cGAS–STING could be a crucial component for the activation of immune cells in the TME of dMMR/MSI-H gastrointestinal adenocarcinomas." (PMID 39242811, 2024). "However, whether and how cGAS-STING pathway mediates the interaction between tumor cells and endothelial cells, as well as the role of cGAS-STING pathway in tumor vasculature remain largely unknown." (PMID 38177099, 2024). "In addition, the efficacy of anti-tumor therapies is dependent on the cGAS-STING signaling." (PMID 37781354, 2023). "However, the non-canonical NF-κB activation downstream to cGAS/STING signaling pathway in tumor-associated DCs (TADCs) during radiation therapy decreases type 1 IFNs level." (PMID 37380989, 2023). "Hence, whether cGAS–STING engagement results in an outcome that is beneficial or detrimental to tumour cell survival depends on the status of each of its downstream pathway components." (PMID 36876871, 2023). "However, the regulatory mechanisms by which cGAS expression suppresses tumor recurrence in patients with CRC remain largely unknown." (PMID 37345163, 2023). "However, cGAS-STING signaling has also been linked to cancer cell survival and tumor progression." (PMID 38203626, 2023). "RT activates multiple immune-associated pathways by damaging tumor cells, including cyclic guanosine monophosphate (GMP)-adenosine monophosphate (AMP) synthase (Cyclic GMP-AMP synthase, cGAS), and stimulator of interferon genes (STING) protein (cGAS-STING pathway)." (PMID 37221584, 2023).
tumor (continued). "Therefore, exogenous laser irradiation and endogenous high level GSH can be used to turn on MPCZ NPs in a responsive manner to generate abundant ROS and Mn2+ in tumor cells, thus efficiently and responsively to activate cGAS-STING signaling pathway and amplify innate immunotherapy." (PMID 37061706, 2023). "Thus, the level of cGAS/STING expression can predict survival in dMMR tumor patients." (PMID 37122745, 2023). "Nevertheless, the threshold of cGAS or STING activities must be maintained at normal levels to ensure effective anti-tumor responses and avoid facilitating the development of malignancy and side effects; therefore, developing STING agonists as adjuvants of cancer vaccines may be beneficial." (PMID 37686127, 2023). "However, the overall clinical benefit still requires careful consideration, because the cGAS/STING pathway, which is induced in response to cytosolic DNA generated by genomic instability, is also associated with immune responses that have anti-tumor effects." (PMID 36706121, 2023). "The findings also suggest that a deficiency of cGAS-STING pathway components in dMMR tumor cells considerably reduces tumor infiltration by CD8+ T cells; as this does not necessarily involve mutation-mediated neoantigens, it demonstrates the conclusions in reverse order." (PMID 36793735, 2023). "Moreover, the expression of cGAS-STING in tumor cells could serve as a potential biomarker for predicting the efficacy of ICI treatment in patients with pMMR/MSS CRC." (PMID 37345163, 2023). "Therefore, one possibility is that a similar mechanism might be involved in the increased frequency of recurrence in patients with pMMR/MSS CRC with low expression of cGAS in tumor cells." (PMID 37345163, 2023). "Therefore, a thorough understanding of the oncogenic or tumor-suppressive effects of cGAS-STING could assist in stratifying cancer patients for treatment." (PMID 37920470, 2023). "Indeed, following IR of tumor cells, the cGAS-STING-IRF3-type I IFN cascade activates DCs, which leads to activation of the adaptive immune response via priming of downstream effector cancer-specific T cell recognition (CD8+) as well as lysing tumor cells locally and at distant sites." (PMID 37511215, 2023). "Since pDNA‐PKcs expression positively correlates with tumor progression, and in the light of our meta‐analysis, it is tempting to hypothesize that in tumors where the cGAS‐STING pathway fuels tumorigenesis, the use of DNA‐PKcs inhibitor may facilitate tumor clearance." (PMID 36574362, 2023). "In addition, cytosolic DNA ingested by dendritic cells from radiation-damaged tumor cells produce cyclic guanine monophosphate-adenosine monophosphate (cGAMP) via cGAMP synthase (cGAS) and stimulate interferon genes (STING) to transcribe type I interferon (IFN)." (PMID 37849983, 2023). "Indeed, many studies have ascribed the influence of cGAS–STING on tumour development and metastasis to the activation of STING signalling in multiple cellular components of the TME other than tumour cells, including astrocytes, mesenchymal stromal cells and phagocytes." (PMID 36876871, 2023). "Notably, IL1B upregulation persisted after LSP + MET treatment, a phenomenon that might also control tumor growth, as a pyroptotic type of cell death via the cGAS-STING pathway was triggered by persistent stimulation of IL1β." (PMID 36765551, 2023). "Given the emerging links between cGAS–STING and CIN in tumours, it is tempting to speculate that by emphasising the CIN- and CIN-associated stress-limiting properties of cGAS–STING activation, chromosomally unstable cancers help maintain a window of CIN that is optimal to their survival." (PMID 36876871, 2023). "In tumour cells, ZnFe2O4 nanoparticles could be disintegrated by responding to high level glutathione, and the released Fe3+ generated reactive oxygen species to induce the DNA leakage into the cytoplasm to stimulate cGAS." (PMID 38264691, 2023).
tumor (continued). "Therefore, the inhibition of the cGAS–STING pathway in tumor cells may induce resistance to chemoimmunotherapy." (PMID 36980689, 2023). "In contrast, cGAS-STING signaling may promote tumor growth and metastasis." (PMID 36936940, 2023). "The anti-tumor effects of RT have been shown to be at least partially dependent on the immune response in vivo, and activation of a type I interferon (IFN) response by the cGAS/STING pathway has been implicated as a critical step in mediating this anti-tumor immune response." (PMID 37312163, 2023). "However, the impact of the expression of cGAS-STING in tumor cells on the infiltration of CD8+ T cells and clinical outcomes in mismatch repair proficient/microsatellite stable (pMMR/MSS) CRC remains largely unknown." (PMID 37345163, 2023). "The downregulation of cGAS-STING in diverse tumor cells may be closely linked to epigenetic modifications, offering a novel theoretical foundation for reactivating the cGAS-STING pathway to enhance anti-tumor immune responses." (PMID 37920470, 2023). "Therefore, an investigation of the IR-associated activation of the cGAS/STING/IFN-1 cascade in non-cancer cells in the tumor microenvironment is also of great interest to support the immunogenic impact of RT in STING-negative or -inactive tumors." (PMID 37834346, 2023). "Thus, when cGAS-STING is activated, tumor cells may alleviate the damage caused by interferon accumulation by releasing both activated and inactivated STING into the cellular foreign body." (PMID 37569723, 2023). "Moreover, PARPis could upregulate PD-L1 in tumor cells by contributing to the activation of the cGAS/STING–IFN-I pathway and suppressing T-cell responses." (PMID 36831435, 2023). "Herein, we report that the biomineralized manganese oxide nanoparticles (Bio-MnO2 NPs) prepared by mild enzymatic reaction could be a promising candidate to synergistically enhance RT and RT-induced immune responses by relieving tumor hypoxia and activating cGAS-STING pathway." (PMID 36144927, 2022). "Additionally, chronic activation of the cGAS-STING pathway has been found to drive tumor metastasis and cancer progression, which may partly elucidate the high malignancy and poor survival of patients with increased DDR scores." (PMID 35720326, 2022). "Specifically, RT of tumor cells induces double-stranded DNA breaks and unique nucleotide adducts that leak into the cytosol and bind to the DNA sensor cyclic guanosine monophosphate-adenosine monophosphate (cGAMP) synthase (cGAS) protein resulting in an increase in intracellular cGAMP." (PMID 36387120, 2022). "Therefore, the distinct roles of the cGAS-STING pathway might be tumor-specific, and future therapies targeting the cGAS-STING pathway should be tailored to each cancer type." (PMID 35983076, 2022). "Radiotherapy usually causes the destruction of nuclear and gene instability in cancer cells, and the accumulated tumor pathological DNA in the cytoplasm may activate the cGAS-STING signal pathway, and then induce congenital immunity and promote the adaptive immune response." (PMID 35889509, 2022). "Radiotherapy may work synergistically with immunotherapy, preclinical evidences indicated that radiotherapy may re-programme tumor microenvironment by promoting the release of tumor neoantigen, activating innate immune response via cGAS/STING pathway and improve immune cell infiltration." (PMID 35296087, 2022). "Notably, COAD had the highest cGAS-STING score while BRCA had the lowest among those tumor types." (PMID 35983076, 2022). "The mechanism of action of the antiangiogenic drug bevacizumab seems less likely to directly impact the immune system by ADCC; however, an indirect effect on tumor vasculatures due to the STING/cGAS pathway could interfere with the bevacizumab antitumor activity." (PMID 36432658, 2022).
tumor (continued). "However, in addition to the anti-tumor and immunogenic effects of the cGAS-STING pathway, this pathway has also been shown to induce pro-tumorigenic factors, such as IL-6 through activation of the NFkB pathway and PD-L1 through activation of the JAK-STAT pathway." (PMID 36387120, 2022). "To test the potential requirement for the activation of the cGAS/STING pathway, which leads to IL-15 production in myeloid cells which have taken up the nanoparticles in vitro, in ONP-302-induced regulation of tumor growth, we examined B16.F10 tumor growth in STING-deficient C57BL/6 mice." (PMID 36059473, 2022). "The other is that broken double-stranded DNA (dsDNA) could be produced in large quantities by irradiated tumor cells that would trigger the cGAS-STING signaling pathway after entering the cytoplasm, and mediate the elimination of damaged tumor cells by immune cells." (PMID 35790987, 2022). "Besides, tumor cell-derived exosomes contain DNA strands, which can induce immune cell responses by STING/cGAS pathway, and consequently, these exosomes may regulate tumor immunity with a possible role in checkpoint immunotherapy." (PMID 36123730, 2022). "According to the recent report on the immunostimulatory activity of HMGB144, we hypothesized that HMGB1 could bind to the concurrently released tumor-derived dsDNA and shuttle them to DCs to activate the cGAS-STING pathway therein after the nanoassembly-induced ICD of tumor cells." (PMID 36167857, 2022). "Thus, cGAS appears to be needed for tumor suppressive responses after exposure to the CCI, AZ82." (PMID 36612150, 2022). "However, how the cGAS-STING pathway might lead to stimulatory immune responses versus oncogenic activities in different tumor types remains largely obscure." (PMID 35983076, 2022). "In addition, it has been reported that in the tumor microenvironment (TME), cancer cells transfer cGAMP into tumor-associated DCs via gap junctions, leading to the activation of pathways downstream of the cGAS-STING." (PMID 36353640, 2022). "Thus, knowing the level of activation of the cGAS-STING pathway within a tumor prior to therapy administration may help inform therapy response." (PMID 36923311, 2022). "Therefore, the activation of cGAS/STING signaling may contribute to anti-tumor immunity in the treatment of HCC." (PMID 36297353, 2022). "Therefore, activation of copper-induced death may reshape tumor immunity in the ccRCC microenvironment by regulating the antigen-presenting process and cGAS-STING signaling." (PMID 36581992, 2022). "Thus, recognition of micronuclei by cGAS may act as a cell-intrinsic immune surveillance mechanism that detects a range of neoplasia-inducing processes." (PMID 34374004, 2022). "IFNA, IFNB and CXCL10 transcript levels were decreased in TRAMP-C2 and DU145 cells transfected with cGAS siRNAs and cGAS-deficient A549, HeLa, and HCT116 cells demonstrating that sensing of cytosolic DNA by cGAS contributes to the constitutive expression of type I IFNs in tumor cells." (PMID 33790360, 2021). "Inhibition of cGAS or STING expression in tumor cells could prevent metastasis in animal models." (PMID 35265630, 2021). "However, the potential effects of the cGAS/STING pathway on radiation-induced changes in tumor cell expression of immune susceptibility markers has not been fully elucidated." (PMID 33995649, 2021). "Moreover, to confirm the anti-tumor effects of RRM2 silencing were mainly due to cGAS/STING pathway mediated CD8 + T cells infiltrations in vivo, T cells depletion by monoclonal antibody treatment could be a better choice." (PMID 33858512, 2021). "Since DNA damage stimuli could trigger an adaptive antitumor immune response by DNA-sensing cGAS-STING-INF-γ pathway or release of tumor-derived antigens, a rational combined anti-CD47 antibody with chemotherapy or radiotherapy could enhance the efficiency of antitumor immunotherapy." (PMID 34512146, 2021).
tumor (continued). "Thus, DDR inhibitors can not only inhibit DNA repair and increase the sensitivity of radiotherapy, but also increase the number of micronucleus and small fragments of DNA in tumor cells induced by radiotherapy, and further activate the cGAS-STING pathway and the expression of type 1 IFN." (PMID 34925345, 2021). "Although the majority of pre-clinical studies using different DDR-targeted agents that have been published seem to support this hypothesis, how cGAS/STING activation affects tumour development is controversial, as it has been shown to either limit or favour tumourigenesis." (PMID 34885119, 2021). "In addition, the frequent necrosis in tumor cells leads to DNA damage and nuclear rupture, and the persistent presence of DNA in the cytoplasm will lead to the chronic activation of cGAS-STING, which has the opposite effect, resulting in the activation of STING-dependent non-normative NF-κB pathway." (PMID 34483930, 2021). "In addition, as STING and cGAS expression levels can vary substantially among human tumor types and the human STING gene has allelic haplotypes encoding for protein variants with reduced activity, G4 binder immunomodulation potency can likely vary among different cancer types and patients." (PMID 34139015, 2021). "Thus, cGAS is critical in immune surveillance or tumor restraint; Apart from acting as an anti-inflammatory and autoimmune regulator, cGAS also modulates autophagy and senescence; it also inhibits homologous recombination repair (HRR) of DSBs in a STING-independent manner." (PMID 37305397, 2021). "Furthermore, PARP inhibition seems to augment cytotoxic T cell tumor infiltration through activation of the cGAS/STING innate immune pathway, leading to increased levels of chemokines, such as CXCL10 and CCL5, that induce the activation and function of cytotoxic CD8+ T cells." (PMID 32046278, 2020). "Thus, even though therapies that leverage cGAS-STING signaling to initiate an anti-tumor response might be less effective in these tumors, viral oncolysis can serve as a viable alternative." (PMID 32774773, 2020). "Indeed, the cGAS–STING pathway is associated with promoting antitumor immune responses, although it should be noted the same pathway can paradoxically facilitate tumor progression in particular contexts." (PMID 33238631, 2020). "However, there have been conflicting reports whether the activation of cGAS–STING signaling inhibits or promotes tumor progression." (PMID 32382015, 2020). "Activated cGAS-STING signals could be detected in both tumor cells and immune cells." (PMID 30935414, 2019). "The dual role of cGAS in chromosomal instability as a tumor suppressor through its activation of the innate immune system and, conversely, as a tumor promoter by inhibiting DNA repair and promoting metastasis might come with important implications for cancer therapy." (PMID 31658669, 2019). "Moreover, cGAS also acts as tumor suppressor independent to immune system signaling." (PMID 31658669, 2019). "Thus, tumor type, location and tumor microenvironment may play significant role in dictating the anti-cancer or carcinogenic role of cGAS/STING pathway." (PMID 29156566, 2017). "In tumor immunity, interferons can induce pyroptosis mediated by caspase-1 or caspase-4/5/11 through NLRP3 or cGAS–STING pathways, releasing IL-1β and IL-18 to promote immune cell infiltration and antitumor responses." (PMID 41601698, 2026). "In cancer, mtDNA released by senescent cells activates the cGAS-STING-NF-κB pathway in myeloid-derived suppressor cells, fostering tumor progression." (PMID 41522347, 2026). "Here, we identify OSBP63, a kind of bromophenol compound, as a potent STING agonist that directly binds the adaptor protein, robustly activates the cGAS–STING pathway, and elicits downstream cytokine production to suppress tumor growth." (PMID 41614892, 2026).